IL13 (interleukin 13)
Diseases named in the same sentence as IL13 in open-access papers (continued):
Sharing a sentence is not in itself a finding about the gene and the disease.
glioblastoma (continued). "Our group has developed and clinically translated an IL13(E12Y) ligand–based CAR targeting the cancer antigen IL13Rα2 for treatment of glioblastoma (GBM)." (PMID 36968221, 2023). "In a phase III clinical trial, interleukin 13-pseudomonas toxin administered via CED showed similar survival in adult glioblastoma (GBM) patients at first recurrence compared to the Gliadel® wafer, the only long-acting GBM treatment approved by the U.S. FDA." (PMID 37375758, 2023). "Therefore, since the D1 peptide could also block the binding of IL13 to the more widespread receptor IL13Rα1, we investigated the presence of IL13Rα1 in different colorectal cancer and glioblastoma cell lines." (PMID 30318506, 2018). "In this study, SEB was fused to interleukin-13 (IL13), which forms a complex with IL13 receptor α2 (IL13Rα2) overexpressed in glioblastoma multiforme (GBM) cells for therapeutic goals." (PMID 39118800, 2024). "We have recently identified PTP1B as a critical mediator in the interleukin 13 (IL-13)/IL-13 receptor α2 (IL13Rα2) pathway involved in colorectal cancer (CRC), ovarian cancer and glioblastoma (GBM) progression." (PMID 37963919, 2023). "In targeting glioblastoma cells, CAR-T cells modified with a targeted-quadruple-mutant of IL13 was combined with fluorescent therapeutic NPs and targeted to IL13Rα2 overexpressed glioblastoma cells." (PMID 35612318, 2022). "Given the heterogeneous expression of antigens on glioblastomas, Hegde et al28 created a CAR‐That joins a HER2‐binding ScFv and an IL13Rα2‐binding IL‐13 mutein to make a tandem CAR exodomain (TanCAR) and a CD28.ζ endodomain." (PMID 34145792, 2021). "DTEGF13 is a bispecific immunotoxin consisting of DT390 fused to EGF and IL-13, made to target a range of solid tumors including glioblastoma, prostate, and pancreatic cancers, which overexpress receptors for both EGF and IL-13." (PMID 31681205, 2019). "Taken together, these results suggest the capacity of the D1 peptide to inhibit IL-13-mediated cell signalling through FAK, Src, AKT and ERK1/2 in colorectal cancer and glioblastoma cell lines and the induction of MT1-MMP in glioblastoma cells." (PMID 30318506, 2018). "Indeed, an IL13Rα2 D1 peptide located at the IL-13 binding site showed strong inhibition capacity for the IL-13/IL13Rα2 signaling cascade in metastatic CRC and glioblastoma." (PMID 33917458, 2021). "In the PRECISE randomized phase III trial, the IL-13-Pseudomonas exotoxin A conjugate (termed IL13-PE38QQR) has produced results similar to those of the Gliadel® wafer, in 296 patients with recurrent glioblastoma, as a result of which the clinical development of this compound was discontinued." (PMID 34063335, 2021). "In a study with glioblastoma patients, cytotoxic T lymphocytes (CTLs) were engineered to express the herpes simplex virus type 1 thymidine kinase (HSV1-tk) alongside a glioblastoma-targeting interleukin-13 zetakine." (PMID 33584676, 2020). "Furthermore, a candidate IL13Rα2 therapeutic peptide was able to inhibit IL-13 signaling capacity in both tumors, CRC and glioblastoma, by inhibiting the Src pathway." (PMID 32098194, 2020). "IL-13Rα2 binds IL-13 with high affinity and has received significant attention in brain tumor therapy because it is overexpressed by high-grade glioblastomas, but not expressed at significant levels by normal brain tissue." (PMID 29168083, 2018). "Regardless of the cell line, the D1 peptide abolished IL-13 effects on invasion, migration and proliferation in both glioblastoma cell lines." (PMID 30318506, 2018). "Also, it was shown that Interleukin-13 (IL-13) induces the 15-LOX-1 expression and activity that resulted in the elevation of 15-LOX-1 metabolites, activation of peroxisome proliferator-activated receptor-gamma (PPAR-γ), initiation of apoptosis in glioblastoma cells." (PMID 34838055, 2021).
glioblastoma (continued). "Similarly, the inhibition of GSK-3β in glioblastoma (GBM)-specific IL13 chimeric antigen receptor expressing T (IL13-CAR-T) cells increased the survival and proliferation of CAR-positive T cells upon activation with IL13Rα2-expressing GBM tumor cells, or soluble target antigen." (PMID 32526891, 2020).
ulcerative colitis (58 papers, 2013 to 2025). An inflammatory bowel disease involving the mucosal surface of the large intestine and rectum. "Increased interleukin-13 (IL-13), an inflammatory cytokine produced by immune cells, has been previously implicated in gut inflammation and ulcerative colitis." (PMID 32635383, 2020). "For example, Crohn’s disease (CD) is associated with excessive IFN-γ/IL-17 and IL-12/IL-23 production, while ulcerative colitis (UC) is associated with excess IL-13." (PMID 32650570, 2020). "In a mouse model of ulcerative colitis using the hapten, oxazolone to induce a transient disease phenotype, blocking IL-13 or using IL-13 gene-deficient mice has been shown to ameliorate or prevent disease induction." (PMID 30460209, 2018). "Mice with oxazolone-induced enteritis are considered a Th2-dominant ulcerative colitis model, and IL-13 produced from iNKTs is an associated cytokine." (PMID 30583538, 2018). "It has been established that EC cells express interleukin (IL)-13 receptor, additionally IL-13 has been implicated in the pathogenesis of ulcerative colitis." (PMID 24015275, 2013). "Oxazolone, on the other hand, has been associated with IL-4 and IL-13 production and a Th2 immune response reminiscent of ulcerative colitis." (PMID 24376661, 2013). "However, IL-13 has also been linked to mediating the host inflammatory cascade responsible for the pathogenesis of ulcerative colitis." (PMID 30460209, 2018). "Furthermore, IL-13, a key effector Th2 cytokine, has been implicated in the pathogenesis of ulcerative colitis in mammals, where it directly contributes to epithelial cell damage by disrupting tight junctions, inducing apoptosis, and impairing cellular restitution." (PMID 40392591, 2025). "IL-13 of the GI tract is associated mainly with ulcerative colitis and eosinophilic oesophagitis 27, and the finding in our study of elevated levels of IL-13 in serum of children with screening-detected coeliac disease may shed new light on the role and function of this particular cytokine." (PMID 25212572, 2015). "Application of a new ultrasensitive technique of quantifying cytokines in plasma to cohorts of patients with ulcerative colitis showed all cytokines examined, except IL‐13 and IL1β, were readily measurable within the linear concentration range in most samples." (PMID 40584280, 2025). "Among these cytokines, IL13 is most effective in patients with ulcerative colitis (UC) and fistulizing Crohn’s disease (CD), which makes anti-IL13 agents a promising therapeutic strategy for the management of inflammatory bowel disease (IBD)." (PMID 37893107, 2023). "In patients with UC, IL-13 showed a significant increase within apoptotic cells and the corresponding apoptotic area (The Th2 colitis model, Oxazolone colitis, resembling ulcerative colitis, is mediated through IL-13-producing NK-T cells)." (PMID 38288119, 2023). "IL-13 plays a role in the pathogenesis of several autoimmune diseases, including rheumatoid arthritis, systemic lupus erythematosus, ulcerative colitis, Sjogren’s syndrome, and multiple sclerosis." (PMID 37513704, 2023). "Previous studies have highlighted a role for the Th2 cytokines IL-4 and IL-13 in mediating acute ulcerative colitis." (PMID 32410852, 2020). "Overexpression of miR-31 and miR-155 regulated interleukin-13 signaling pathway via targeting interleukin-13 receptor α-1 in ulcerative colitis." (PMID 32386518, 2020). "Currently, there is very little known about the involvement of IL-4/IL-13 signalling on smooth muscle cells in ulcerative colitis." (PMID 32410852, 2020). "It has been assumed that IL-13 is a key effector cytokine in ulcerative colitis and that enterohepatic bile acid circulation is disturbed by BA malabsorption in inflammatory bowel diseases." (PMID 32846954, 2020).
ulcerative colitis (continued). "IL-13, a key effector Th2 cytokine in ulcerative colitis, also shows the ability to impair epithelial barrier function by affecting epithelial apoptosis, tight junctions, and reconstitution velocity." (PMID 31886308, 2019). "On the contrary, ulcerative colitis is usually considered a “Th2-like” disease characterized by increased amounts of IL-5 and IL-13." (PMID 31886308, 2019). "Previous studies have shown the role of IL-13 in gut defense and inflammation and a toxic effect on colonic epithelial cells and on the epithelial barrier in ulcerative colitis." (PMID 31214623, 2019). "Despite this evidence, recent clinical trial data suggests that specifically blocking the receptor through which IL-13 signals, IL-4 receptor-alpha (IL-4Rα) in ulcerative colitis patients, is insufficient in protecting them from disease outcome." (PMID 30460209, 2018). "It has been reported that the number of NKTs is increased in the intestinal mucosa of patients with ulcerative colitis, and IL-13 production is enhanced." (PMID 30583538, 2018). "The potential benefits of ameliorating IL-13 production in ulcerative colitis remains an interesting approach in treating disease." (PMID 30460209, 2018). "In ulcerative colitis, IL-13 has been described as a key effector cytokine acting on epithelial cell function and initiating apoptosis." (PMID 30460209, 2018). "The potential role of IL-13 signaling independently of IL-4Rα in mediating ulcerative colitis is highlighted as an important consideration when targeting the signaling mechanisms of IL-13 for therapeutic approaches." (PMID 30460209, 2018). "This review describes the role of IL-13 in ulcerative colitis and current treatment strategies that target IL-13." (PMID 30460209, 2018). "In particular, IL-13 has a central role in the pathogenesis of ulcerative colitis (UC), a major type of inflammatory bowel disease (IBD) that has a significantly increased risk of CRC." (PMID 27533463, 2016). "Increased p-STAT6 has also been shown in ulcerative colitis (UC) patients and is involved in IL-13-induced colon epithelia dysfunction." (PMID 27533463, 2016). "IL-13 is a cytokine of increasing interest to gastroenterologist due to its developing role in inflammation and fibrosis in ulcerative colitis (UC) and Crohn's disease (CD)." (PMID 27533463, 2016). "One TH2-type cytokine [interleukin (IL)-13] is thought to play a unique and critical role in ulcerative colitis in gut mucosal inflammatory response; however, PFOA-related effects on IL-13 expression have not been described." (PMID 23735465, 2013). "In ulcerative colitis the high levels of IL-13 are shown to be derived from variant CD1d-restricted NKT cells and IL-13 has been shown to have a toxic effect on colonic epithelial cells." (PMID 23690672, 2013). "Both the innate and adaptive immune systems are implicated in IBD pathogenesis, with CD being associated with Th1/Th17 responses, producing cytokines like IL-17, IFN-γ, and TNF-α, whereas ulcerative colitis features a Th2 response, with IL-5 and IL-13 activating B cells and NK T cells." (PMID 40507438, 2025). "In addition, interleukin 13 is involved in gastrointestinal diseases such as ulcerative colitis and eosinophilic esophagitis." (PMID 40771803, 2025). "Therefore, the aim of the present study was to investigate the protective effect of myrrh in an experimental inflammatory situation, namely, under the influence of IL-13, one of the key cytokines in ulcerative colitis." (PMID 38044939, 2023). "However, ulcerative colitis is mediated by Th2 cells, and excessive IL-13 production can be observed." (PMID 36425101, 2022). "Furthermore, IL-13 is upregulated in ulcerative colitis patients and has been shown to increase colon epithelial permeability by inducing apoptosis." (PMID 32410852, 2020). "The role of interleukin-13 in mediating ulcerative colitis remains under scrutiny." (PMID 30460209, 2018).
ulcerative colitis (continued). "These mechanistic insights into disease pathogenesis could provide additional host directed IL-13 drug targets to alleviate the symptoms of ulcerative colitis." (PMID 30460209, 2018). "Interestingly, type II NKT cells seem to promote intestinal inflammation and mediate a pathogenic response when both CD1d expression and the frequency of IL-13 producing type II NKT cells are increased in mice as well as patients with ulcerative colitis." (PMID 26136748, 2015). "There are several reports of increased GM-CSF in Crohn’s disease (CD) and ulcerative colitis (UC) patients, and concomitant Th17 and IL-5 and IL-13 T cell responses have been observed in ileal CD suggesting a more polyfunctional T cell response in certain patients." (PMID 26200014, 2015). "In IBD, tissue damage occurs in areas heavily infiltrated with activated CD4+ T lymphocytes, and Th1 cell-derived cytokines are important mediators of tissue damage in Crohn’s disease, while Th2-type cytokine IL-13 may play an essential role in ulcerative colitis." (PMID 36139127, 2022). "We have previously shown that the T helper- (Th-) type 2 cytokines, Interleukin- (IL-) 4 and IL-13, mediate CD4+ T cell- or B cell-driven inflammation in the oxazolone-induced mouse model of ulcerative colitis." (PMID 32410852, 2020). "Ulcerative colitis in rats increased the expression of TNF-α, MMP9 and IL-13." (PMID 38321559, 2024). "IL-5 and IL-13 correlate with TH2 polarization and TH2-mediated ulcerative colitis." (PMID 38395946, 2024). "MD3 was upregulated in human ulcerative colitis and MD3 expression could be increased in HT-29/B6 cells by IL-13 via the IL13Rα1/STAT pathway." (PMID 35563847, 2022). "However, studies on the imbalance of TJs induced by IL-13 in intestinal Th2-dominant immunity, such as ulcerative colitis, are still lacking." (PMID 38732497, 2024). "However, therapeutic attempts of neutralizing IL-13 in ulcerative colitis patients have yielded no benefits." (PMID 34136502, 2021). "It is noteworthy that type II NKT cells involved in ulcerative colitis in humans are also reactive to lysosulfatide, but in contrast to the liver type II NKT cells, they secrete IL-13 and not IFNγ." (PMID 26136748, 2015).
autoimmune disease (49 papers, 2006 to 2025). A disorder resulting from loss of function or tissue destruction of an organ or multiple organs, arising from humoral or cellular immune responses of the individual to their own tissue constituents. "Although IL-4 and IL-13 are generally described as anti-inflammatory, both have been implicated in promoting antibody-mediated autoimmune diseases, such as MS and EAE." (PMID 31404142, 2019). "The involvement of IL4 and IL13 gene polymorphisms in a number of autoimmune diseases prompted us to investigate their role along with HLA-DQ and DR genotypes in genetic susceptibility of T1DM in a completely different population (Kuwaiti Arab children) which has a high incidence rate of T1DM." (PMID 37090926, 2023). "Recent studies have implicated IL-4 and IL-13 in the development of various autoimmune diseases." (PMID 34831223, 2021). "IL-13 polymorphisms are associated with autoimmune diseases and also increase susceptibility to MS." (PMID 27304970, 2016). "It is tempting to speculate if hormonal-driven epigenetic changes to IL-13+ T cells in females may have broader consequences for susceptibility to type 2 T cell-associated autoimmune diseases that predominantly occur in females, e.g., lupus and multiple sclerosis." (PMID 20667106, 2010). "IL-13, a cytokine found to be increased in patients with autoimmune diseases, was increased in MC1 patients with “low” compared to “high” intradiscal C.acnes GCNs (FDR ​= ​0.02)." (PMID 38322145, 2024). "miR-155 modulates the IL-17/IL-23 axis in autoimmune diseases, and is believed to influence the M1/M2 balance in macrophages by modulating the IL-13 effect." (PMID 39518908, 2024). "Although IL-17E is known to induce a Th2-mediated allergic response by stimulating IL-4, IL-5 and IL-13 production, several studies highlight its proinflammatory role in skin and autoimmune diseases." (PMID 38799435, 2024). "In this context, interleukin induction properties of mimic peptides were assessed using available web servers for IL-4, IL-6, and IL-13, as interleukins are involved in autoimmune disorders." (PMID 37513704, 2023). "Further, a relationship between IL-13 and fibrosis has also been reported in many chronic infectious and autoimmune diseases, which is reported to signal through the IL-13α2 receptor to induce TGF-β1 production as a central mediator of fibrosis." (PMID 34858903, 2021). "IL-4 and IL-13 are anti-inflammatory cytokines, which play key roles in preventing inflammation and autoimmune diseases." (PMID 33953716, 2021). "It is well known that IL-13 plays a key role in regulating the anti-parasitic response and is a primary factor that induces fibrosis in many chronic contagious and autoimmune diseases." (PMID 31801572, 2019). "Abnormal expression of IL13 is found in many autoimmune diseases with an inflammatory response, while IL6 is released mainly by white blood cells and activates the synthesis of acute phase proteins, like CRP." (PMID 31194785, 2019). "IL-13 is also involved in the pathogenesis of autoimmune diseases and cancer." (PMID 40076424, 2025). "The evaluated cytokines can be classified into three broad groups: the proinflammatory Th-1 cytokines: IL-2, IFN-γ, and TNF-α; the counterbalancing Th-2 cytokines: IL-4, IL-5, IL-10, and IL-13; and the Th-17 cytokine IL-17A, which is actively involved in several autoimmune diseases including MS." (PMID 38932415, 2024). "Furthermore, IL-13 is reported to be increased in the synovial fluid of patients with rheumatoid arthritis, which is an autoimmune disease targeting the synovial tissue." (PMID 38711706, 2024). "The fact that IL-13 is highly expressed in Hodgkin/Reed-Sternberg (H/RS) tumor cells and blood cells of patients with autoimmune rheumatic diseases indicates its role in the pathogenesis of neoplastic and autoimmune diseases." (PMID 37041520, 2023).